CD44 (CD44 molecule (IN blood group))
Diseases named in the same sentence as CD44 in open-access papers (continued):
Sharing a sentence is not in itself a finding about the gene and the disease.
atherosclerosis (continued). "Macrophages, which are important propagators of atherosclerosis and primary phagocytes in atherosclerotic plaques, express several HA receptors, such as CD44, ICAM-1, LYVE-1, RHAMM, and TLR-4." (PMID 33003609, 2020). "For example, it is overexpressed on activated macrophages that play central roles in the development of atherosclerotic plaques, implying that CD44 is a useful target in atherosclerosis for molecular imaging and targeted drug delivery." (PMID 33003609, 2020). "In a murine study of atherosclerosis, reduced recruitment of macrophages to sites of inflammation was reported, confirming that CD44 promotes the recruitment of macrophages." (PMID 31226944, 2019). "Flavonoids have also been reported to increase the collagen content of plaque lesions, and decrease expression of CD44, suggesting an ability to promote atherosclerosis plaque stability." (PMID 28742839, 2017). "In contrast, we previously reported that CD44 promotes auto-inflammatory disease progression in a mouse model of atherosclerosis." (PMID 26029216, 2015). "This interpretation is supported by studies that indicate that Cd44 is an early mediator of atherosclerosis and is upregulated by pro-atherosclerotic cytokines." (PMID 25115202, 2014). "An intuitive next step in studying the role of CD44 is to test its importance in atherosclerosis in vivo." (PMID 25059316, 2014). "It is significant that the role of CD44 in inflammation has been described and demonstrated to be important for radiation-induced atherosclerosis in ApoE−/− mice." (PMID 25059316, 2014). "The second approach repeated our NEO analysis using Cd44 transcript levels as our phenotype of interest and the peak SNP for the atherosclerosis QTL, rs3671635, to anchor the analysis." (PMID 25115202, 2014). "Using a series of bioinformatics analysis, we further prioritize the genes in this pathway and identify Cd44 as a critical mediator of the atherosclerosis." (PMID 25115202, 2014). "Additional, studies are needed to clarify the role of CD44 in atherosclerosis and differences between humans and mice in CD44’s role in regulating in the inflammatory response." (PMID 25115202, 2014). "The hyaluronan receptor CD44 plays a critical role in the progression of atherosclerosis through multiple mechanisms, including inflammatory cell recruitment and cellular activation." (PMID 18560564, 2008). "SMAD3, TNF, MMP2, MMP9, CTGF, CD44 and AKT1 are associated with atherosclerosis." (PMID 37328880, 2023). "Cd44 has a critical role in the recruitment of leukocytes and is upregulated and functionally activated during inflammation, and is potentially important for the recruitment of macrophages and their retention in atherosclerosis." (PMID 34027348, 2021). "A study showed that, TNPO1 may play an indispensable role in developing atherosclerosis by regulating the transport of CD44." (PMID 34138931, 2021). "In rat atherosclerosis PCR array, Abca1, Bax, Bcl2, Bcl2a1, Cd44, Fabp3, Hbegf, Lypla1, Ptgs1, Selplg, Tgfb2, Tnc, and Vegfa had reverse trend between WT and MU groups, while the trends of Bcl2l1, Bid, Birc3, Cxcl1, Fas, Fn1, Itga2, Itga5, Lif, Nfkb1, Nr1h3, Ppard, and Sod1 were consistent." (PMID 34545275, 2021). "Numerous studies suggest that the CD44 cell adhesion molecule may promote atherosclerosis by mediating the recruitment of inflammatory cells into platelets and activation of vascular cells." (PMID 34335086, 2021). "Expression of CD44 was found to be upregulated in areas prone to atherosclerosis." (PMID 34335086, 2021). "On the other hand, low molecular weight-HA has been shown to promote inflammation through binding to alternative receptors including CD44 and could accelerate atherosclerosis." (PMID 31912264, 2020). "Notably, the levels of CD44, Hyals, and OSs are highly related to the progression of many types of inflammatory diseases such as atherosclerosis, cancer, and traumatic brain injury." (PMID 33003609, 2020).
atherosclerosis (continued). "Moreover, gene expression profiling in the aorta of CD44 knockout mice compared to a wild type led to the discovery that CD44 regulates focal adhesion formation, extracellular matrix deposition, and angiogenesis, critical processes for atherosclerosis." (PMID 34335086, 2021). "Thus, self-assembled HA-NP could be a potential therapeutic agent for treatment of not only T2D and atherosclerosis, but also other CD44-mediated inflammatory diseases." (PMID 33003609, 2020). "Nevertheless, the ability to alter macrophage polarization via CD44 offers a potentially new mechanism to target the inflammatory response in vivo, in the context of tumor progression as well as other inflammatory conditions, such as wound healing, lung injury, and atherosclerosis." (PMID 26029216, 2015). "CSF1 can contribute to atherosclerosis development via fatty streak formation and progression to complex fibrous lesions, and CD44 may enhance atherosclerosis pathogenesis via reactive oxygen species, whereas neuregulin and ERBB4 are necessary for vascular growth and development." (PMID 18987747, 2008). "For instance, some proteins related to atherosclerosis were down-regulated in SF, such as ARG2, CD14, CD44, engulfment, and cell motility protein 1 (ELMO1), neutrophil gelatinase-associated lipocalin (LCN2), MPO, S100A8, or S100A9." (PMID 34572333, 2021). "Interestingly, CD44 was highly expressed in both the atherosclerotic and macroscopically intact adjacent tissue from humans and could indicate an important difference in the regulation of atherosclerosis in humans and mice." (PMID 25115202, 2014). "In a mouse model of atherosclerosis, many CD4+ T cells in lymph nodes and atherosclerotic plaques exhibit a memory T cell phenotype, characterized by the expression of surface markers such as CD44." (PMID 39473192, 2025). "Consequently, the CD44-targeted and H2O2-responsive polymeric micelles loaded with SIM possess excellent therapeutic effects and low side effects in atherosclerosis treatment." (PMID 33287831, 2020). "CD44 and VCAM1 were increased in an atherosclerosis mouse-model too." (PMID 28323859, 2017). "Moreover, there is growing evidence that, apart from its role as a drug carrier, an empty HA-NP with no drug can exert therapeutic effects in T2D and atherosclerosis by suppressing the proinflammatory response in peripheral tissues by blocking CD44." (PMID 33003609, 2020).
metastatic disease (40 papers, 2009 to 2026). "CD44 is a known marker of cancer stem cells, which are implicated in the initiation of metastatic disease, a process which has been associated with high c-Myc expression in other cancer types." (PMID 40395327, 2025). "This study confirmed that adding OTP, CD44, and Ki-67 to the carcinoid classification improved the identification of patients who are at risk for metastatic disease." (PMID 35805004, 2022). "In STS, expression of cell-surface antigen CD44 has been associated with local recurrence and, in particular, the isoform CD44v6 has been correlated with metastatic disease." (PMID 24491153, 2014). "Next, the in-house patient primary and metastatic tumours were compared for their CD44 expression levels using IHC." (PMID 37174052, 2023). "The expression of CD44 was significantly upregulated in metastatic compared to the primary tumours, as demonstrated in the in-house primary and metastatic tumours using IHC." (PMID 37174052, 2023). "Although CD44 expression has traditionally been used as a marker of metastatic disease, recent publications have demonstrated that cellular expression of CD44 fluctuates during cancer progression." (PMID 34579762, 2021). "The first-in-human phase I clinical trial of an anti-CD44 monoclonal antibody (RG7356) for CD44-expressing local advanced or metastatic tumors was recently completed." (PMID 32194856, 2020). "Nearly all the ex vivo expanded mesoderm-derived fibroblasts from normal breast, and CAFs from primary and brain metastatic tumors expressed the common mesenchyme markers CD44, CD90, CD105, CD166, and CD140β." (PMID 28649646, 2017). "Among these markers, CD97, CD104, CD107a, and CD121a are significantly more expressed in the CD133+ and CD44+ double positive cells of human ovarian ascites tumor cells (Ascites_133+44+) than those from primary ovarian or metastatic tumors." (PMID 27655682, 2016). "This linkage was more prominent in samples from recurrent and metastatic tumors with more than 25% CD44+/CD24- cells." (PMID 22762532, 2012). "Our findings are consistent with a previous report which showed by histological analysis that purified CD44+ PCa cells, which possess many features of CSC, generated more invasive and metastatic tumors than the corresponding CD44− cells." (PMID 22328933, 2012). "CD44 standard isoform expression was unchanged in PDAC LNs, whereas multiple CD44 variant isoforms (v4-v10) were significantly reduced and associated with metastatic disease and poor survival, particularly CD44v5, v6, v7, and v10." (PMID 41827845, 2026). "CD44-negative expression can be considered a hallmark of metastatic disease in prostate adenocarcinoma." (PMID 37461792, 2023). "In addition, strong and diffuse membrane staining for CD44 was observed in 100% of prostatic small cell neuroendocrine carcinomas, a more aggressive tumors and often present as locally advanced or metastatic disease." (PMID 29029419, 2017). "EMT markers in primary tumors may be expressed less than in metastatic tumors, especially in advanced-stage disease, as has been found for some CD44 isoforms." (PMID 27590006, 2016). "The proportion of CD44+/CD24- tumor cells was significantly associated with lymph node involvement (P = 0.026) and PR status (P = 0.038), and was correlated with strong PR status in patients with recurrent or metastatic tumors (P = 0.046) and with basal-like features (p = 0.05)." (PMID 22762532, 2012). "We must also acknowledge that we were unable to confirm intratumor heterogeneity because there were only limited numbers of surgically resected specimens of the recurrent or metastatic tumors for repeat CD44/CD24 staining, which may be considered in future studies." (PMID 22839505, 2012). "We detected the expression of CD44 in tumor cells of the metastases by multiple immunofluorescences and analyzed the correlation between EGR1 and CD44 in the tumor components of the metastatic tumor (mesothelial cells were positioned by HBME1)." (PMID 38385088, 2024).
metastatic disease (continued). "We found six genes such as SPP1, VEGFA, POSTN, RUNX2, CD44, and FOXO1 that were consistently overexpressed in patients with bone metastasis compared to non-metastatic tumors." (PMID 36424413, 2022). "Expression of cortactin, CD44, NBS1, CXCR4, Snail and VEGF in patients with metastatic disease has been correlated to the development of distant metastases." (PMID 24212639, 2011). "The upregulation of these two critical ovarian stem-cell markers CD44 and ALDH1L1 in omental metastatic tumors points to a potential interaction between the omental mesothelial cell niche and tumor-derived Notch-Jagged2 signaling in the development of CSC features by tumor cells." (PMID 38575576, 2024). "But CC-CAFs-induced enhancement of metastasis was decreased when CD44 was knocked down, the injection of CC-CAFs alone did not result in formation of metastatic tumors." (PMID 31367190, 2019). "The CD44 results agreed very well with our small set of patient samples, the staining of CD147 in patient samples was not as intense as that in cell lines, although it was upregulated in the metastatic tumor as compared to the primary tumor." (PMID 28910304, 2017). "While a number of studies have shown a correlation between the expression of CSC markers such as CD133, CD44, CD166, Lgr5 and Bmi1 and survival, much less is known about the correlation of expression of these markers and the CSC phenotype in metastatic disease." (PMID 21318087, 2011). "Similarly, CD44 expression level was markedly higher in patients diagnosed with M1 (metastatic disease) compared to those diagnosed with M0 (non-metastatic disease) (p < 0.01)." (PMID 40069421, 2025). "While individual CSC markers (and combinations thereof) such as CD44, CD166 and CD133 have been used to identify colorectal CSCs in specific patient populations, the prognostic and predictive utility of CSC markers remains uncertain, particularly in completely resected or widely metastatic disease." (PMID 21318087, 2011). "CD44 and ALCAM expression was detected in both mice that developed (WHIM17 and WHIM12) and mice that did not develop (WHIM23) metastatic disease." (PMID 29291741, 2018).
gastric tumors (39 papers, 2013 to 2025). "For example, the normal transcript for CD44 was expressed in normal gastric tissue, and the upregulation of its splice variant is associated with invasion and metastasis of gastric tumors." (PMID 33563334, 2021). "Additionally, CD44 positive gastric tumors were associated with larger tumor size, a lower grade of differentiation, tumor relapse, lymph node invasion, distant metastasis and reduced survival." (PMID 34069167, 2021). "Besides, the presence of CD44+ cancer cells at the invasive front of gastric tumors is associated with poor prognosis, and the presence of circulating CD44+ tumor cells in patients correlates with tumor stage and depth, vascular invasion, metastasis and reduced survival." (PMID 35326607, 2022). "Additional examples are the CV-1 peptide targeting CD44 in gastric tumors, plectin-1 targeted peptides for pancreatic ductal adenocarcinoma (PDAC), and hepsin-specific peptides for prostate cancer imaging and detection." (PMID 41008874, 2025). "In a gastric tumor xenograft animal model, CD44+ cells exhibited cancer stem cell characteristics, and CD44 suppression led to decreased tumor growth." (PMID 40864800, 2025). "The CV-1 peptide, which specifically binds to CD44 (involved in tumor progression and drug resistance), is a promising probe for early molecular imaging of CD44v-positive gastric tumors." (PMID 41008874, 2025). "It has been shown that there are different patterns of protein expression between cardia and non-cardia carcinoma in terms of several markers, such as CD44, Mucin 1 (MUC1), and Cyclin-Dependent Kinase Inhibitor 2A (CDKN2A)." (PMID 35096085, 2022). "In GC, the ALDH+CD44+/CD166+ signature has been proposed as the most tumorigenic phenotype among the cells derived from human primary gastric tumors." (PMID 35326607, 2022). "CLSM showed that the fluorescence signals (Rh6G-FD (red dot) and FA-TH (orange dot)) of the prepared NPs were co-localized and interacted with P-selectin (purple dot) and CD44 (green dot) in gastric tumor tissue (white arrows)." (PMID 34575403, 2021). "Liver metastases formed by GC10 cells also contained significantly more CD44-positive cells than stomach tumors." (PMID 31010193, 2019). "In GC, previous studies have reported that CD44-positive cells generate gastric tumors with a higher frequency than CD44-negative cells when implanted in the stomach." (PMID 31010193, 2019). "The efficacy test of the drugs using gastric tumor organoids of Apc1638N mice showed that the CD44 and ALDH1A3 cancer stem cell markers were induced by FOLFOX, but not by KYA1797K." (PMID 30965636, 2019). "In this study, we used sphere cultures in vitro, and tumor formation in mice, to successfully validate the self-renewal and tumor-initiating capacity of CD44+HER2+ GCSCs from primary gastric tumors." (PMID 28284008, 2018). "CD44 knock-down decreased the level of FGFR2 expression and inhibited gastric tumor growth, whereas CD44 activation led to upregulation in FGFR2 expression." (PMID 29747682, 2018). "Our results, for the first time, show that YM155 inhibits gastric tumor growth by inhibition of expansion of CD44+ gastric CSCs." (PMID 26771139, 2016). "In another experimental model on cancer stem cells with the mark of CD44, it was observed that hyaluronic acid-modified PAMAM-entrapped gold nanoparticles delivering the METase gene suppressed the gastric tumor growth (hyaluronic acid was used to recognize the cells with the mark of CD44)." (PMID 34641519, 2021). "In addition, the resistance and recurrence upon treatment with chemotherapy were strongly associated with the enrichment of CD44 and ALDH1A3 CSC markers in the FOLFOX-treated tumor organoids (tumoroids) derived from Apc1638N mouse gastric tumors." (PMID 30965636, 2019).
gastric tumors (continued). "It has been well-documented that high expression of CD44 predicts poor prognosis of various tumors including breast, brain, colon, pancreatic, and gastric tumors, indicating that CD44 may be a valuable prognostic marker and therapeutic target for cancers." (PMID 31497537, 2019). "CD44 genetic knockdown or xCT inhibitors could suppress the development of metaplasia and subsequent gastric tumor growth." (PMID 27708226, 2016). "A potential contribution of chemotherapy to the activation of CSCs was shown by the enrichment of CD44 and ALDH1A3 in the tumoroids derived from gastric tumor tissues from Apc1638N mice, which reduced their size upon FOLFOX treatment." (PMID 30965636, 2019). "In this animal model, increases of CD44 and ALDH1A3 CSC markers were also observed in gastric tumors compared with their levels in adjacent normal tissue." (PMID 30965636, 2019). "The expansion of CD44+ gastric cells in mice was suggested to be induced by a cooperative effect of PGE2-mediated inflammation and Wnt signaling, resulting in the development of gastric tumors." (PMID 30884828, 2019). "In one gastrointestinal cancer mouse model, CD44-positive gastric tumor cells expressed a set of antioxidant genes at higher levels as compared with CD44-negative tumor cells." (PMID 26322272, 2015).